FAM171A1 (family with sequence similarity 171 member A1)
Description:
Involved in the regulation of the cytoskeletal dynamics, plays a role in actin stress fiber formation.
Synonyms: APCN; C10orf38; FLJ12884
Tractability: Antibody: UniProt places it where antibodies can reach, with high confidence; its Gene Ontology location is reachable by antibodies, with high confidence; UniProt predicts a signal peptide or a membrane-spanning region; the Human Protein Atlas places it where antibodies can reach. PROTAC: its protein half-life has been measured.
Gene: Protein-coding gene on chromosome 10 (15,211,643 to 15,371,289, reverse strand). Ensembl gene ENSG00000148468.
Subcellular location: Cell membrane
Subcellular location (Human Protein Atlas): Plasma membrane; Nucleoplasm
Gene Ontology:
Molecular function: protein binding
Biological process: regulation of cell shape; stress fiber assembly
Cellular component: plasma membrane
Genetic constraint (gnomAD): Loss-of-function variants: 23 observed, 73.11 expected, observed/expected ratio (o/e) 0.31, 90% interval 0.22 to 0.45. The upper end of that interval is the gene's LOEUF score, 0.45, which puts it in group 1 of 6, group 1 being the genes least tolerant of losing a copy. Missense variants: 1,126 observed, 1,176 expected, observed/expected ratio (o/e) 0.96, 90% interval 0.91 to 1.01. Synonymous variants: 514 observed, 510.24 expected, observed/expected ratio (o/e) 1.01, 90% interval 0.94 to 1.08.
Homologues: Orthologues: chimpanzee FAM171A1 (99% identical), macaque FAM171A1 (99% identical), mouse Fam171a1 (92% identical), rabbit FAM171A1 (92% identical), pig FAM171A1 (91% identical), guinea pig FAM171A1 (90% identical), rat Fam171a1 (89% identical), dog FAM171A1 (86% identical), tropical clawed frog fam171a1 (69% identical), zebrafish fam171a1 (47% identical). Paralogues in human: FAM171A2 (37% identical), FAM171B (28% identical).
Diseases named in the same sentence as FAM171A1 in open-access papers:
FAM171A1 is named in the same sentence as 12 diseases in open-access papers, as found by Europe PMC text mining. Sharing a sentence is not in itself a finding about the gene and the disease. The quoted sentences say what the papers report.
breast carcinoma (6 papers, 2017 to 2021). "Here for the first time, we provide the molecular basis of the noted loss of FAM171A1 that is highly expressed in ERα-deficient breast cancer cells." (PMID 30631046, 2019). "The underlying mechanism of the noticed upregulation of FAM171A1 in TNBC cells includes reduced levels of miR590-5p in TNBC cells, which otherwise targets FAM171A1 in ERα-positive breast cancer cells, and thus the loss of miR590-5p regulates FAM171A1 in TNBC cells." (PMID 30631046, 2019). "Other genes selected by Rlogreg, namely KISS1, IGF2BP2, CALCA, PLA1A, and FAM171A1, have been reported to be related to breast cancer or other types of cancer." (PMID 32795265, 2020). "For example, rs13129525 which ranks 9 is located on the FAM171A1 gene which is suggested to be affected in breast cancer." (PMID 32957998, 2020). "In brief, results presented here suggest that the FAM171A1 is an important TNBC-specific gene as its level profoundly modulates the aggressiveness of breast cancer cells." (PMID 30631046, 2019). "Mechanistically, we show that miR590-5p is an ERα-responsive gene and that ERα stimulates the expression of miR590-5p, which, in turn, downregulates FAM171A1 in ERα-positive breast cancer cells." (PMID 30631046, 2019). "Functional studies showed that elevated expression of FAM171A1 in breast cancer cells contributes to the invasiveness and stemness of breast cancer cells." (PMID 30631046, 2019). "This strategy led us to a single gene, known as FAM171A1—which is widely expressed in the basal-like breast cancer cell lines and tissue samples." (PMID 30631046, 2019). "Here we identify FAM171A1 as a preferentially expressed gene in basal-type breast tumors, and its levels closely correlate with the aggressiveness of breast cancer cells." (PMID 30631046, 2019). "Additionally, we explored the role of ERα and its newly identified target here, the miR590-5p, in the regulation of FAM171A1 expression in ERα+ breast cancer and TNBC cells." (PMID 30631046, 2019). "To understand the functional significance of the noticed increased expression of FAM171A1 in breast cancer biology, we evaluated the effect of depleting endogenous FAM171A1 in MDA-MB-231 cells on its invasiveness, anchorage-independent growth, and ability to form mammospheres." (PMID 30631046, 2019). "However, the nature of the upstream regulation of FAM171A1 and biological significance of FAM171A1 in breast cancer remains poorly understood, and this is being addressed in the present study." (PMID 30631046, 2019). "Kaplan–Meier survival curve analyses of breast cancer patients by the PrognoScan, the Survival Express, and the KM plotter revealed an increased expression of FAM171A1, and that its levels correlate well with an overall poor survival of the breast cancer patients." (PMID 30631046, 2019). "We tested the hypothesis that ERα might be responsible for the noted reduced expression of FAM171A1 in ERα-positive breast cancer cells." (PMID 30631046, 2019). "In summary here, we demonstrate FAM171A1 as a candidate gene overexpressed in TNBC cell lines and TNBC tumors as compared to ERα-positive breast cancer cells." (PMID 30631046, 2019). "They found high expression of Fam171a1 in triple-negative breast cancer and that elevated expression of Fam171a1 correlated with aggressiveness of breast cancer cells." (PMID 34481452, 2021). "Here, we identified FAM171A1, member (A1) of the family with sequence similarity 171, as an overexpressed candidate gene in TNBC cells and tumors as compared to estrogen receptor-alpha (ERα) positive breast cancer." (PMID 30631046, 2019). "To further examine the role of FAM171A1 in supporting the stemness of breast cancer cells, we next generated stable clones from MCF-7 and T47D breast cancer cells which otherwise express no or low levels of FAM171A1." (PMID 30631046, 2019).
breast carcinoma (continued). "Next, we set to understand the basis of noticed reduced expression of FAM171A1 in ERα-positive breast cancer cells as compared to ERα-negative breast cancer cells." (PMID 30631046, 2019). "However, Kaplan–Meier survival analyses of miR590-5p (a suspected modifier of FAM171A1, this study) show that high expression of miR590-5p may lead to better overall survival rates of breast cancer patients, highlighting its significance in breast cancer biology in physiologically relevant setting." (PMID 30631046, 2019). "Together these findings suggest that ERα stimulates miR590-5p, which, in-turn, represses FAM171A1 expression, and that the noticed increased expression of FAM171A1 might be associated with low levels of miR590-5p in ERα-negative TNBC breast cancer cells." (PMID 30631046, 2019). "This analysis revealed that in general, ESR1 expression exhibits a negative correlation with FAM171A1 in breast cancer datasets, and a similar trend was also observed for PGR in respective cell lines as well as carcinoma databases other than breast cancer datasets." (PMID 30631046, 2019). "Next, we screened the status of FAM171A1 in a panel of TNBC and non-TNBC breast cancer cell lines." (PMID 30631046, 2019). "We found high levels of FAM171A1 in the basal-type TNBC cell lines such as MDA-MB-231, SUM149, SUM159, BT549, HCC1937, and Hs-578T as compared to non-TNBC breast cancer cell lines such as MCF-7, T47D, ZR-75, and SKBR3 as well as normal mammary epithelial cell line, HMEC (Supplementary 4A)." (PMID 30631046, 2019).
triple-negative breast carcinoma (4 papers, 2020 to 2021). An invasive breast carcinoma which is negative for expression of estrogen receptor (ER), progesterone receptor (PR), and human epidermal growth factor receptor 2 (HER2). "Furthermore, FAM171A1 (APCN) expression has also recently been shown to correlate with invasive phenotypes and poor overall survival in triple-negative breast cancers." (PMID 35047985, 2020). "FAM171A1 is known as a potential biomarker in triple-negative breast cancer." (PMID 32854705, 2020).
sarcopenia (3 papers, 2022 to 2024). Progressive decline in muscle mass due to aging which results in decreased functional capacity of muscles. "Further investigations are needed to reveal other functional characterizations of FAM171A1, and the role of FAM171A1 in the pathogenesis of sarcopenia would be an important future research direction." (PMID 36147639, 2022). "In this research, six genetic biomarkers closely associated with sarcopenia, including ARHGAP36, FAM171A1, GPCPD1, MT1X, ZNF415, and RXRG, were identified by WGNCA and LASSO analysis, which were used to future diagnose and screen for sarcopenia." (PMID 36147639, 2022). "Finally, six hub genes with AUC exceeding 0.9, including GPCPD1, MT1X, ARHGAP36, FAM171A1, ZNF415, and RXRG, were defined as diagnostic biomarkers of sarcopenia." (PMID 36147639, 2022). "We found the AUC values of GPCPD1, MT1X, ARHGAP36, FAM171A1, ZNF415, and RXRG on the validation dataset were 0.928, 0.75, 0.978, 0.961, 0.811, and 0.906, indicating that the six biomarkers had high diagnostic accuracy for sarcopenia." (PMID 36147639, 2022). "Moreover, six hub genes with AUC exceeding 0.9, including ARHGAP36, FAM171A1, GPCPD1, MT1X, ZNF415, and RXRG, were confirmed as diagnostic biomarkers for sarcopenia." (PMID 36147639, 2022). "Compared to normal samples, the expression levels of both MT1X and ARHGAP36 were upregulated in sarcopenia samples, while GPCPD1, FAM171A1, ZNF415, and RXRG showed lower expression in sarcopenia samples." (PMID 36147639, 2022). "Additionally, in patients with sarcopenia, MT1X and ARHGAP36 were upregulated, whereas FAM171A1, GPCPD1, ZNF415 and RXRG, were downregulated, demonstrating high diagnostic accuracy for sarcopenia and potential as predictive markers for screening." (PMID 38337720, 2024).
breast invasive carcinoma (1 paper, 2020). "In breast invasive carcinoma (BRCA), FAM171A1 showed the highest average ΔPCC in the group-specific network." (PMID 32854705, 2020).
gastroschisis (1 paper, 2022). Gastroschisis is marked by viscera protruding, without a covering sac, from the fetal abdomen on the right lateral base of the umbilicus. "A group of researchers reported on a mutant mouse with gastroschisis that had a mutation in Slit3, as well as an extra point mutation in Fam171A1, a related family member that has 35% amino acid identity with FAM171B." (PMID 36248192, 2022).
cancer (4 papers, 2019 to 2021). A tumor composed of atypical neoplastic, often pleomorphic cells that invade other tissues. "As ERα (ESR1) expression strongly parallels to the PR (PGR; Progesterone receptor), we next tried to assess the correlation between the ESR1, PGR, and FAM171A1 in published cell line datasets as well as in other cancer datasets." (PMID 30631046, 2019). "GSEA reveals an overlap between the high level of FAM171A1, upregulated stem cell gene signatures as well as activated gene signatures for TGFβ/Smad and Wnt/β-catenin pathways, suggesting a possible involvement of FAM171A1 in the modulation of cancer stem cells." (PMID 30631046, 2019). "In silico and data-mining analyses suggest that FAM171A1 has been predicted to interact with FAM171B, PCDHGB1, TNFRSF17, TMEM, CTDSPL, and NTRK1, many of which have been already implicated in various cancers suggesting most likely its possible role in the tumorigenesis." (PMID 30631046, 2019). "Analysis revealed that high expression of FAM171A1 correlates with upregulated stem cell gene signatures and therefore, may be involved in the regulation of cancer stem cell functions." (PMID 30631046, 2019). "FAM171A1, also known as astroprincin (APTN), was reported to overexpress in brain astrocytes and involve in regulation of cytoskeletal dynamics, hence the cell shape and growth of cancer cells." (PMID 34013637, 2021).
tumor (4 papers, 2020 to 2022). "Our study identified novel iCCA‐associated genes FAM171A1, ONCUT1 and PHYHIPL and implied their tumour suppressing roles and prognosis values." (PMID 34013637, 2021). "Key hub genes SLC2A1, CDH3 and EFHD2 showed increased expression across the tumour stage and were correlated with poor survival, whereas decrease of FAM171A1, ONECUT1 and PHYHIPL was correlated with better survival." (PMID 34013637, 2021). "Consistent with the trend of overall expression of hub genes, expression of FAM171A1, ONECUT1 and PHYHIPL decreased across the tumour stage." (PMID 34013637, 2021).
adenocarcinoma (1 paper, 2015). A common cancer characterized by the presence of malignant glandular cells. "For adenocarcinoma specifically, DM was observed in promoters [hypermethylated RASL12; SPTAN1, mir-26a, hypomethylated NQO1, SIRPB1, NF1A] and gene bodies [hypermethylated AKAP13, ANK family, PRKCE, ROS1; hypomethylated FAM171A1, PARK2, BCAS3, RHOJ] and many others." (PMID 26683690, 2015).
FAM171A1 also shares sentences with these, for which no sentence is quoted: astrocytoma (1 paper); colon cancer (1); melanoma (1); nodular melanoma (1).